LRRC37A (leucine rich repeat containing 37A)
Synonyms: LRRC37A1; KIAA0563; LRRC37
Tractability: Antibody: UniProt predicts a signal peptide or a membrane-spanning region.
Gene: Protein-coding gene on chromosome 17 (46,292,733 to 46,338,077, forward strand). Ensembl gene ENSG00000176681.
Subcellular location: Membrane
Subcellular location (Human Protein Atlas): Vesicles
Gene Ontology:
Cellular component: membrane
Genetic constraint (gnomAD): Loss-of-function variants: 1 observed, 3.13 expected, observed/expected ratio (o/e) 0.32, 90% interval 0.11 to 1.42. That is too few expected variants to judge how well the gene tolerates losing a copy. Missense variants: 7 observed, 64.98 expected, observed/expected ratio (o/e) 0.11, 90% interval 0.06 to 0.2. Synonymous variants: 3 observed, 22.28 expected, observed/expected ratio (o/e) 0.13, 90% interval 0.06 to 0.35.
Homologues: Orthologues: chimpanzee LRRC37A3 (95% identical), rat Prp2l1 (42% identical), mouse Lrrc37a (41% identical), mouse Lrrc37 (39% identical), rat Lrrc37a (39% identical). Paralogues in human: LRRC37A2 (99% identical), LRRC37A3 (94% identical), LRRC37B (37% identical).
Diseases named in the same sentence as LRRC37A in open-access papers:
LRRC37A is named in the same sentence as 9 diseases in open-access papers, as found by Europe PMC text mining. Sharing a sentence is not in itself a finding about the gene and the disease. The quoted sentences say what the papers report.
schizophrenia (2 papers, 2023 to 2025). A major psychotic disorder characterized by abnormalities in the perception or expression of reality. "Regarding intelligence and schizophrenia, MAAT identified 21 genes with high association levels in these two traits, where the significant function of ACTR1A, C22orf46, CKB, CYP2D6, LRRC37A, NCK1, and ZMAT2 have been well validated in large-scale GWAS studies." (PMID 39905509, 2025). "Notably, aside from intelligence and schizophrenia, LRRC37A also plays important roles in other psychiatric diseases." (PMID 39905509, 2025).
bipolar disorder (1 paper, 2018). A disorder of the brain that causes unusual shifts in mood, energy, activity levels and the ability to carry out day-to-day tasks. "For example, leucine-rich repeat containing genes (which include LRRC37A, implicated in neuroticism, and LRRC57, implicated in bipolar disorder) are known to be key organizers of excitatory and inhibitory synapse formation." (PMID 30419947, 2018).
cervical cancer (1 paper, 2025). A primary or metastatic malignant neoplasm involving the cervix. "Using genome-wide analysis, we identified thousands of similar competition sites across the genome, many near cancer-related genes like PPP1R15B and LRRC37A, which are linked to poor survival in cervical cancer patients." (PMID 40953061, 2025). "High expression levels of either PPP1R15B or LRRC37A were correlated with poor survival outcomes in patients with cervical cancer." (PMID 40953061, 2025).
neurodegenerative disease (2 papers, 2023 to 2025). A disorder of the central nervous system characterized by gradual and progressive loss of neural tissue and neurologic function. "We demonstrate that the hemizygous deletion of the endogenous SVA_67 in CRISPR edited cell lines was associated with differential expression of several genes at the MAPT locus associated with neurodegenerative diseases including KANSL1, MAPT and LRRC37A." (PMID 37840928, 2023). "Other genes such as SPI1, LRRC37A, NSF, and TCTA have also been reported to have effect on neurodegenerative diseases." (PMID 39905509, 2025).
cancer (1 paper, 2025). A tumor composed of atypical neoplastic, often pleomorphic cells that invade other tissues. "We validated competition at two CBSs in the promoter and found it likely regulates cancer-related genes PPP1R15B and LRRC37A." (PMID 40953061, 2025).
LRRC37A also shares sentences with these, for which no sentence is quoted: COVID-19 (2 papers); Alzheimer disease (1); cognitive decline (1); psychiatric diseases (1).